TEX19 (testis expressed 19)
Diseases named in the same sentence as TEX19 in open-access papers (continued):
Sharing a sentence is not in itself a finding about the gene and the disease.
cancer (continued). "TEX19 is a recently characterized player within the family of cancer testis antigens, which are normally expressed in the germ cell compartment of the normal testis, but also in a wide range of cancers, with current evidence pointing towards an oncogenic function of these proteins." (PMID 32758242, 2020). "To explore the possibility that TEX19 acts as a protein coding gene transcriptional regulator in cancer cells, we carried out RNA sequencing on total polyA-RNA extracted from untreated SW480 cells and cells treated with a TEX19 siRNA." (PMID 28446200, 2017). "Human TEX19 is a recently identified CT gene, but a functional role for TEX19 in cancer has not yet been defined." (PMID 28446200, 2017). "Cancerous tissue has heterogeneous regions that have high levels of TEX19 or none/low levels of TEX19, which fits with emerging models of tumour heterogeneity." (PMID 28446200, 2017). "This approach, however, was untenable as many data sets had an imbalance of negative vs. positive TEX19 expressing cancers, negating statistical analysis." (PMID 28446200, 2017). "The biological meaning of this finding is still unknown but indicates TEX19 may not behave solely as a cancer testis antigen." (PMID 32758242, 2020). "Indeed, in other cancer cells lines we tested PIWIL1 is not expressed and yet TE transcripts exhibit a measurable change upon TEX19 depletion, which supports a TEX19-dependent, PIWI-independent pathway." (PMID 28446200, 2017). "We could detect no expression of paralogues in H460, with A2780 expressing PIWIL2 and relatively low levels of PIWIL4; however, the levels of neither were significantly altered by TEX19 depletion, suggesting that TEX19 regulation of PIWI gene expression may not be universal in all cancer cell types." (PMID 28446200, 2017).
tumor (10 papers, 2017 to 2025). "Mouse Tex19.1 expression is activated in response to DNAhypomethylation in multiple contexts (Hackett etal., 2012), and in humans TEX19 is a cancer testis antigenexpressed in multiple types of tumor where it is associated with poor cancerprognosis." (PMID 28806172, 2017). "Finally, overall survival analysis of high verses low TEX19 expressing tumours indicates that TEX19 expression is linked to prognostic outcomes in different tumour types." (PMID 28446200, 2017). "We cannot, however, exclude the possibility of low levels of nuclear TEX19 in these cells and we did observe occasional TEX19 foci associated with DAPI stained nuclear material in the tumour tissue." (PMID 28446200, 2017). "Despite the relatively mild proliferative reduction observed in vitro, TEX19-shRNA induction in mice resulted in significant reduction of tumour volume, indicating that TEX19 expression is required for tumour development." (PMID 28446200, 2017). "Whilst most of the TEX19 they observed in these samples appeared to be cytoplasmic, there are clearly cells within the tumours that exhibit some nuclear staining with the anti-TEX19 antibodies employed." (PMID 28446200, 2017). "In addition, shTEX19 cells were arrested in G1 phase, which indicated that TEX19 is essential for tumor cell proliferation." (PMID 41233852, 2025). "To determine whether TEX19 plays a role in self-renewal/proliferation in tumours in vivo we developed SW480 and HCT116 cell lines carrying an inducible shRNA cassette." (PMID 28446200, 2017). "The heterogeneous distribution of TEX19 indicates two possibilities; firstly, TEX19 may be ‘on’ during the early stages of tumourigenesis and becomes deactivated during the evolution of the tumour, or, alternatively, TEX19 only becomes activated in specific regions as the tumour develops and grows." (PMID 28446200, 2017). "A body of emerging evidence has revealed that meiotic chromosome regulator genes, including REC8, SMC1β, RAD21L1, TEX19, HORMAD1, and SYCP3, are inappropriately activated to modulate chromosome maintenance and segregation in tumor development, maintenance, and spread." (PMID 34150762, 2021). "Remarkably, in the germline tumour cell line, NTERA2, anti-TEX19 staining is predominantly nuclear, which could infer a link to germline/stem capabilities for TEX19." (PMID 28446200, 2017). "It is known that tumours can evolve and acquire a high degree of intra- and inter-tumour heterogeneity, and so database samples may also include information acquired from tumour regions that do not express TEX19." (PMID 28446200, 2017).
TEX19 also shares sentences with these, for which no sentence is quoted: kidney cancer (2 papers); colorectal tumour (1); embryonal carcinoma (1); glioblastoma (1); male infertility (1); neuroblastoma (1); prostate adenocarcinoma (1); prostate carcinoma (1); renal carcinoma (1); rhabdomyosarcoma (1).